SMC2 (structural maintenance of chromosomes 2)
Diseases named in the same sentence as SMC2 in open-access papers (continued):
Sharing a sentence is not in itself a finding about the gene and the disease.
cancer (22 papers, 2014 to 2025). A tumor composed of atypical neoplastic, often pleomorphic cells that invade other tissues. "These genes, including Smc2, Mcm3, Ccnd1, Rasal2, Mcm6, and Mad2l1, are linked to cancer progression and metabolic regulation." (PMID 39272991, 2024). "Firstly, SMC2 and SMC4 (i.e. hCAP-E and hCAP-C), the core subunits of human condensin I and condensin II, have been shown to be associated with some malignant tumors." (PMID 29467813, 2018). "Finally, a recent HotNet2 Pan-Cancer analysis suggested that multiple cancers harbor rare mutations in SMC2, SMC4, NCAPD2, NCAPD3, NCAPH2 and NCAPG2, supporting a tumor-suppressor role for condensin proteins." (PMID 36169232, 2022). "Moreover, SMC2 overexpression and mutations in some of the condensing subunits had been reported in cancer genomes, suggesting that functional alterations affecting condensin complexes are common in tumorigenesis." (PMID 32098204, 2020). "Therefore, the phosphorylation of SMC2 might be an unknown mechanism for the Pol I inhibitors to treat tumors, indicating that the mutations of SMC2 T574 might reduce the sensitivity of Pol I inhibitors in cancer treatment." (PMID 41203590, 2025). "Delivering specific antibody against the SMC2 intracellularly is an effective strategy, which aims to reduce cancer malignancy by targeting cancer stem cells (CSC), the tumoral subpopulation responsible of tumor recurrence and metastasis." (PMID 41203590, 2025). "SMC2 has a dual role in cancer development, being involved in mitotic cell division and potentially promoting cancer." (PMID 39272991, 2024). "These genes, such as ANXA1, SMC2, KIF23, and DDX5, are primarily associated with cancer cell proliferation, metastasis, and poor prognosis." (PMID 35184675, 2022). "SMC2 over-expression has been related with tumorigenesis and cancer malignancy and its inhibition is regarded as a potential therapeutic strategy even though no drugs are currently available." (PMID 32098204, 2020). "Altogether, the present results suggest that the proposed nanosystem gathers ideal features to ensure the intracellular delivery of Ab-SMC2 into cancer cells." (PMID 32098204, 2020). "YCG1/NCAPG and SMC2/SMC2 are components of the condensin complex, which are overexpressed in cancer." (PMID 31660150, 2019). "Of these, key cancer-associated genes shown to be upregulated by the SySa fusion were downregulated by TAK-981 treatment, including CDX2, HOXA10, SUZ12, TYMS, AURKB, and HOXC10 and SMC2." (PMID 40804185, 2025). "The profound CIN observed with loss of SMC2 suggests that this protein may also be a prime therapeutic target for treating TNBC and other cancers with the same dependencies." (PMID 37201585, 2023). "Secondly, hypomorphic expression or no expression of SMC2 (hCAP-E) is implicated in cancer pathogenesis." (PMID 34557090, 2021). "For example, SMC2 is involved in mitotic cell division and new evidence indicates that it might have a cancer-promoting effect." (PMID 33460400, 2020). "As a result, SMC2 has been studied as a new molecular therapeutic target for cancer treatment." (PMID 29467813, 2018). "SMC2 is involved in mitotic cell division and might have a cancer-promoting effect." (PMID 33460400, 2020). "In the case of new potential markers, the ZWINT and CONDENSIN I subunits NCAPH, SMC2, and SMC4 all showed similar expression levels displayed by markers in the first circuit, even sharing the same clustering of cancer types." (PMID 40430225, 2025). "Tumorsphere formation assays were performed using HCT116 and MDA-MB-231 cancer cells treated with PM-CON:SMC2, Ab-SMC2 and control PM." (PMID 32098204, 2020). "Aiming to validate SMC2 as a CSC target, SMC2 was silenced in different cancer cell lines (HT116, MDA-MB-231 and PANC-1, from colorectal, breast and pancreatic origin) using RNA interference technology." (PMID 32098204, 2020).
cancer (continued). "Using publicly available patient derived datasets obtained from TCGA, we determined that all eight condensin genes (SMC2, SMC4, NCAPD2, NCAPD3, NCAPG, NCAPG2, NCAPH, and NCAPH2) are frequently altered in at least 12 common cancer types." (PMID 31357676, 2019). "Except for the SMC2 gene, knockdown of the other 10 genes in SU86 cells significantly altered activities, based on the luciferase assay for at least one of the 10 cancer related signaling pathways." (PMID 24483146, 2014). "Of note, the combination of a classical chemotherapeutic agent with Ab-SMC2 was non-deleterious for both encapsulated 5-FU and PTX formulations offering the possibility of eliminating both subpopulations simultaneously, CSC and “bulk” or differentiated cancer cells." (PMID 32098204, 2020).
tumor (11 papers, 2018 to 2025). "We discovered a new phosphorylation site on SMC2 and provided a new idea for tumor treatment strategy targeting SMC2." (PMID 41203590, 2025). "SMC2 silencing by siRNA arose as the most straightforward approach since a previous report by our group showed effective in vivo tumor growth inhibition after ex vivo silencing of the SMC2 gene in tumor cells." (PMID 32098204, 2020). "The most important carcinogenic mechanism and cellular dysfunctions at this stage of CRC are as follows: MIR133B is modified by DNA methylation to downregulate GDNF and SMC2, inhibiting tumor proliferation and migration." (PMID 32211020, 2020). "SMC2 block emerges as a promise strategy to complement the current therapies based on chemotherapeutic drugs, intending not only to attack bulk tumor cells but also the remaining CSC." (PMID 32098204, 2020). "Moreover, mutation of the protein SMC2, may impair the natural expression and promote tumor growth." (PMID 32211020, 2020). "Owing to the epigenetic effect, the target gene SMC2 promotes tumor apoptosis and inhibits the cell cycle; the target gene POU2F1 inhibits cell proliferation; and the target gene GDNF inhibits cell migration and proliferation." (PMID 32211020, 2020). "The expression of SMC2 modified by MIR133B could downregulate the control of tumor proliferation, migration, and apoptosis." (PMID 32211020, 2020). "Our results suggest that the combination of drugs and Ab-SMC2 delivery might cooperate in the eradication not only of bulk tumor cells but also of cells with stemness properties." (PMID 32098204, 2020). "More importantly, it is possible to conclude that by combining PM, drugs and Ab-SMC2, we can make an important contribution, not only to the treatment of the primary tumor, but also in the eradication of the CSC population responsible for tumor recurrence and the metastatic spread of the disease." (PMID 32098204, 2020). "We found that increased expression of SMC2, SMC3, and SMC4 might play a significant role in HCC, and could be useful as molecular markers to identify high-risk patients, Our results also provide insights for further research of SMC family members as potential tumor therapeutic target in HCC." (PMID 36281130, 2022). "As the phosphorylation of SMC2 T574 abolished the function of Condensin in mitosis by interfering the SMC2/SMC4 binding, the molecules mimicking the T574 phosphorylation might provide a new potential strategy for tumor therapy." (PMID 41203590, 2025). "SMC2, SMC3, and SMC4 are also related to tumor purity and immune infiltration levels of HCC." (PMID 36281130, 2022). "In addition, consistent with previous research results, we also found that SMC1A, SMC1B, SMC2, SMC3, SMC4, and SMC6 were overexpressed at the mRNA level in HCC when compared with non-tumor cells." (PMID 34527684, 2021). "Because eradicating CSC in tumors is becoming a great challenge for designing new treatments, we focused in the potential synergism of delivering Ab-SMC2 together with either PTX or 5-FU against tumor cells in non-adherent conditions." (PMID 32098204, 2020).
infection (2 papers, 2023). The state of being infected such as from the introduction of a foreign agent such as serum, vaccine, antigenic substance or organism. "DEGs in SMC2 were induced in B1a/B2 silenced plants relative to EV following P. gregata infection or mock infection." (PMID 38259908, 2023).
adenocarcinoma (1 paper, 2016). A common cancer characterized by the presence of malignant glandular cells. "Gene-expression analysis in adenocarcinomas based on microarray data showed that VRK1 was correlated with members of the mitotic cell-cycle gene network, including CENP-A, CENP-K, CENP-N, CENP-Q, Bub1, BubR1, SMC2, and CAP-G." (PMID 27231315, 2016).
SMC2 also shares sentences with these, for which no sentence is quoted: glioma (2 papers); Haemorrhagic Septicaemia (2); liver cancer (2); pyothorax (2); Alzheimer disease (1); chronic myeloid leukemia (1); familial restrictive cardiomyopathy-6 (1); Fanconi anemia (1); gastric cancer (1); glaucoma (1); glioblastoma (1); HCMV infection (1); heart defects (1); lung adenocarcinoma (1); malignant fibrous histiocytoma (1); Meckel-Gruber syndrome (1); pleomorphic liposarcoma (1); prostate carcinoma (1); round cell liposarcoma (1).